KRAS (KRas proto-oncogene, GTPase)
Diseases named in the same sentence as KRAS in open-access papers (continued):
Sharing a sentence is not in itself a finding about the gene and the disease.
tumor (continued). "In the 43 cases with available baseline tumor and blood samples, high KRAS mutation abundances in both tumor (OS, P = 0.016; PFS, P = 0.046) and blood samples (OS, P < 0.001; PFS, P < 0.001) were significantly associated with poorer survival." (PMID 38378604, 2024). "Alterations in several tumor genes, such as mutations in KRAS, STK11, and KEAP1, have been suggested as potential biomarkers for the ICI response in patients with NSCLC." (PMID 39037971, 2024). "Risk factors for bone metastases include the location of the primary tumor, the age of the patients, KRAS mutations and the degree of tumor differentiation." (PMID 38283131, 2024). "NSCLCs with KRAS mutations can be good candidates for immunotherapy because of the high tumor mutation burden." (PMID 39385301, 2024). "Our results demonstrated specific binding of HLA-G12V/CD3 BiTE to tumor cells with an HLA-A2/KRAS G12V mutation and T cells." (PMID 38752985, 2024). "In this section, we noticed that different types of KRAS mutated variants associated with different types of cancer influence the pathogenicity and regulate other factors, namely tumor-suppressive factors, cell-cycle regulators, and immune-response factors." (PMID 39056802, 2024). "Additional significant associations were observed with BRAFV600E mutation (18.5% of methylated, compared to 6.4% of unmethylated tumours, p = 0.003) and KRAS mutations (37.0% of methylated tumours, compared to 26.4% of unmethylated tumours, p = 0.049)." (PMID 38716804, 2024). "This mutation leads to the constitutive activation of the KRAS protein, promoting dysregulated signaling pathways that contribute to tumor growth and progression." (PMID 39518114, 2024). "Researchers are also exploring mRNA and viral vector-based vaccines to enhance the delivery and immunogenicity of tumor-associated antigens like KRAS, CEA, and others [1378,1379,1380]." (PMID 39273409, 2024). "Experimental evidence suggests that BI-3406 reduces the formation of GTP-loaded KRAS and restricts the growth of most tumor cells driven by KRAS variants at positions G12 and G13." (PMID 38734764, 2024). "The ability of CD4+ T cells to recognize neoantigens from mutations in oncogenes like HER2 and KRAS further supports their role in targeting tumor-specific antigens." (PMID 39457373, 2024). "This key word underscored the clinical imperative for gene expression profiling in KRAS-mutated neoplasms, as these mutations frequently co-occur with additional genomic alterations." (PMID 39252322, 2024). "Microsatellite instability (MSI) status and KRAS/NRAS/BRAFV600E mutation status were concordant among all multiregional samples from each tumor with CMS heterogeneity." (PMID 38773143, 2024). "Some patients received a vaccine that contained other KRAS G12 mutations in addition to the KRAS G12 mutation expressed by the autologous tumor." (PMID 39484723, 2024). "In seventy patients who underwent surgery with curative intent, 37 showed KRAS mutations in surgical margins that histologically were free of tumor." (PMID 38607041, 2024). "EGFR mAb associated PFS benefit was larger in those with KRAS WT tumours if they were aged 70 or younger (HRadj 0.68, p < 0.001) compared to those over 70 (HRadj 0.93, p = 0.465)." (PMID 38402342, 2024).
tumor (continued). "In tumor context, KRAS mutation leads to sustained activation of its pathway rendering a transformed state, i.e., cell proliferation, survival and migration." (PMID 38474109, 2024). "The potential ineffectiveness of ICI treatment in NSCLC is explored through the impact of SMARCA4/KRAS co-mutations on the tumor microenvironment." (PMID 39063938, 2024). "MRTX1133 demonstrated in vivo efficacy in tumour models harbouring KRAS-G12D mutations, with greatest preclinical efficacy seen in pancreatic ductal adenocarcinoma (PDAC)." (PMID 39372214, 2024). "The presence of the oncogenic mutation KRAS G12 was detected in both the tumour tissue and the cfDNA to suggest the circulating nucleic acids were potentially of tumour origin." (PMID 39578455, 2024). "To date, the mechanistic link between KRAS mutation and tumor sidedness also remains to be assessed." (PMID 39335120, 2024). "Tumor growth is triggered by mutations and subsequent inactivation of tumor suppressor genes that cooperate with KRAS oncogene mutations." (PMID 38183010, 2024). "We studied the combined impact of KRAS mutational status and tumor size on overall survival (OS) in patients with stage I-II NSCLC." (PMID 38884086, 2024). "An accrual target of 29 patients will receive autologous DCs with mutant KRAS peptides according to the patient’s tumor mutation and HLA subtype (NCT03592888)." (PMID 38576709, 2024). "These highlight the importance of avoiding the assumption of universal applicability of resistance mechanisms to KRAS inhibitors across different tumor types and KRAS mutation variants, as it oversimplifies the complexity of the issue." (PMID 39704172, 2024). "The tumor genomic status in mCRC was determined for KRAS and NRAS, BRAFV600E mutations, ERBB2 and microsatellite instability (MSI)/mismatch repair (MMR)." (PMID 38978742, 2024). "Among d-MMR tumors, KRAS mutation was associated with increased tumor-stroma ratio (TSR; P-value = 0.040), lower grade (P-value <0.001), and reduced median epithelial TIL density (P-value = 0.003)." (PMID 38709069, 2024). "This indicates a shift toward early immune evasion and KRAS mutations induce multiple cytokines to promote and maintain this tumor promoting environment in invasive disease." (PMID 38576709, 2024). "Direct sequencing of 150 tumor samples was conducted to identify the prevalence of KRAS exon 2 mutations among CRC patients from western Mexico." (PMID 39001385, 2024). "Although our study was limited in size, we observed a trend where tumor organoids with KRAS mutations provoked a stronger immune response than those with epidermal growth factor receptor (EGFR) mutations." (PMID 39475596, 2024). "The prognosis of PDAC patients appears to be dependent on the specific subtype of KRAS mutation present in the tumor." (PMID 39457426, 2024). "They compared the immune cell infiltration, tumor mutational burden, HLA gene expression, and checkpoint-related genes between the KRAS-mutated and wild-type samples." (PMID 39125664, 2024). "While the GSEA similarly identified increased KRAS signaling in this case, this tumor harbors a BRAF mutation, downstream of KRAS." (PMID 38791940, 2024).
tumor (continued). "It is known that the KRAS gene is mutated in a variety of neoplasms, including tumors in lungs, the stomach, the colon, and the endometrium." (PMID 38255325, 2024). "Genetic alterations in KIR and HLA gene loci affect NK cell tumor surveillance, and KRAS mutations are linked to low TIL density and tumor immunogenicity." (PMID 39335203, 2024). "Overall, an expression profile of genes that promote inflammation, mutations in the KRAS gene, large duct type, an advanced tumor stage, and elevated levels of CEA and CA19-9 predict a poor prognosis." (PMID 39061233, 2024). "Connecting KRAS mutations with tumor-promoting inflammation and immune modulation caused by KRAS leads to immune escape in the TME." (PMID 38338768, 2024). "GPR31 has also been reported to regulate the membrane association of KRAS and play an important role in KRAS-dependent tumor survival and proliferation." (PMID 38505262, 2024). "Here, we investigate the prognostic value of combining survival data on KRAS mutation status and tumor size in stage I-II NSCLC." (PMID 38884086, 2024). "Several studies have pointed out that the occurrence of KRAS gene mutations is related to an increased CD8+ T lymphocyte infiltration in the tumor microenvironment (TME)." (PMID 38397927, 2024). "The most common tumor-associated KRAS mutations include G12D (39.2%), G12V (32.5%), G12R (17.1%), and Q61H (4.8%)." (PMID 38610868, 2024). "Taken together, targeted inhibition of PD-L1 and KRAS seems very plausible, firstly because immune checkpoint blockade is often more successful in cancers with high tumor burden such as KRAS-mutated tumors." (PMID 39201772, 2024). "The most striking finding in the study is the significant correlation between KRAS mutations and the type of tumor growth (p-value = 0.035)." (PMID 38465160, 2024). "For example, KRAS and PIK3CA mutations exist within the same tumor; conversely, KRAS and BRAF mutations are mutually exclusive." (PMID 39056802, 2024). "The tumor microenvironment (TME) associated with KRAS-mutant tumor cells is highly immunosuppressive." (PMID 39301544, 2024). "Several negative prognostic factors were identified, such as genes’ expression profile promoting inflammation, mutations in the KRAS gene, advanced tumor stage, and elevated levels of oncological markers." (PMID 39061233, 2024). "Under normal conditions, KRAS cycles between active and inactive states; however, mutations result in constitutive activation, fueling uncontrolled tumor growth." (PMID 39770538, 2024). "In this study, we showed that habitat-derived radiomic features are superior to conventional metabolic parameters and whole tumor region radiomic features in predicting KRAS/NRAS/BRAF mutations in CRC patients." (PMID 38342905, 2024). "Analysis of the percentage and the absolute number of these cells revealed that only CD56bright NK cells were higher in both tumor and tumor plus stroma in the group of KRAS mutation than in the WT." (PMID 38292189, 2024).
tumor (continued). "In the present study, we validated a combined amplification refractory mutation system (ARMS) and high-resolution melting analysis (HRMA) technique for detecting mutations in codon 12 of KRAS in PDAC tumor and plasma samples and assessed its prognostic value." (PMID 39456638, 2024). "KRAS missense mutations were identified in the bulk and/or epithelial-enriched cored tumor samples in 14 patients." (PMID 38291365, 2024). "Key to this is the understanding of tumour molecular biology and clinically relevant mutations, such as KRAS, BRAF, and microsatellite instability (MSI), which can predict poorer overall outcomes and a poorer response to systemic therapy." (PMID 39001441, 2024). "The major KRAS mutations, including G12C, G12D, and G12V, are crucial drivers in the development of multiple tumor types." (PMID 39263575, 2024). "Its expression correlates with BRAF and KRAS mutations, poor differentiation, and advanced tumour stages, marking it as a significant prognostic marker." (PMID 39456841, 2024). "Circulating tumor DNA (ctDNA) can reveal mutations in genes such as KRAS, NRAS, and BRAF and help tailor personalized treatment strategies." (PMID 38790167, 2024). "In agreement with previous studies, we also found that KRAS mutations detected in tumor and plasma seem to hold prognostic value, allowing for patients to be split into two categories—better and worse prognosis—according to type of KRAS mutations." (PMID 39456638, 2024). "Further, we compared the effects of each pUMAP cluster on genes associated with critical HT29 tumor biomarkers: KRAS, BRAF, CDH1, CYNNB1, and MET." (PMID 39605490, 2024). "Another pan-KRAS inhibitor that blocks nucleotide exchange to prevent the activation of wild-type KRAS and a broad range of KRAS mutations showed tumor-suppressive effects in vivo." (PMID 38756650, 2024). "KRAS mutations represent a critical area of focus because they are frequently associated with tumor proliferation and survival." (PMID 39439803, 2024). "So, patients with liver metastases with tumor budding and/or KRAS mutational status respond poorly to anti-EGFR therapy." (PMID 38248029, 2024). "Recent findings of several groups, including ours, support the existence of a functional, clinically impactful heterogeneity of KRAS-mutated tumours." (PMID 38261067, 2024). "SS detected KRAS mutations in 51.1% of tumor samples (n = 45): G12D in 22, G12V in 14, G12R in 7, and G12C in 2 patients." (PMID 39456638, 2024). "The concordance of CRC mutations in both tumor tissue and plasma cfDNA was also studied, which underlined the concordance of 96% KRAS and 100% BRAF mutations." (PMID 38770216, 2024). "For most of the patients with serial samples, we can only make educated guesses about why we see fluctuations in the appearance of ERBB2 amplification and/or KRAS activating mutations based on the degree of tumor shed, as detailed above." (PMID 38406801, 2024).
tumor (continued). "Oncogenic KRAS mutations regulates several aspects of tumor growth and development including promoting tumor growth, metastasis, angiogenesis, resisting apoptosis, promoting immune evasion and also contributing to resistance to therapies." (PMID 38982514, 2024). "In our study, we identified five patients with repeat biopsies and KRAS G12C mutations identified in a subsequent tumor sample (three metachronous, two synchronous)." (PMID 39195317, 2024). "Consistent with this, we evaluated 24 fresh-frozen CRC tissue samples and the matched adjacent normal tissues and 239 fresh-frozen CRC tumor tissues and verified that F. nucleatum abundance was associated with KRAS mutation." (PMID 38402201, 2024). "Consistent with the deep and durable RAS signaling modulation, daily RMC-6236 treatment resulted in dose-dependent antitumor activity in a series of human tumor xenograft models harboring prevalent KRAS mutations, i.e., KRASG12D, KRASG12V, and KRASG12C." (PMID 38593348, 2024). "Nevertheless, enriched KRAS signaling gene sets have been linked to inflammation, a favorable tumor immune microenvironment, and improved survival in triple-negative breast cancer." (PMID 38481800, 2024). "Combining MEK with PDL1 inhibitors resulted in tumor regression in mouse models in KRAS-mutated CRC." (PMID 39080202, 2024). "Pancreatic ductal adenoma (PDAC) is characterized by marked tumor-related inflammation, including macrophage infiltration and epithelial mutations in the KRAS gene." (PMID 39457573, 2024). "We demonstrated here that PDAC 3D-cultured organoids with KRAS mutations were dominantly covered in increased fucosylated glycans, pointing towards novel treatment targets and/or tumor markers." (PMID 38528852, 2024). "One strategy is to stratify patients according to KRAS mutational status together with other key prognostic factors, such as tumor size." (PMID 38884086, 2024). "The discovery of erastin, a small molecule compound with selective cytotoxicity against KRAS-mutated tumor cells, unveiled ferroptosis as a form of iron-ion-dependent cell demise induced by lipid peroxide accumulation." (PMID 39065721, 2024). "Tumor size and KRAS variant allele frequency (VAF) differed between rim-enhancing (n = 12) and nonrim-enhancing (n = 29) PDACs with a cutoff of 17.22%." (PMID 38525415, 2024). "Given that KACs, like early tumour cells, acquired Kras mutations, we examined the effects of targeted KRAS(G12D) inhibition on these organoids." (PMID 38418883, 2024). "Cell viability assays using CellTiter‐Glo reagents showed that Gal9‐KO significantly sensitized tumor organoids harboring ALK translocation to crizotinib (organoid #2) or those with KRAS mutations (organoid #3) to cisplatin." (PMID 38528665, 2024).